RN7SL604P (RNA, 7SL, cytoplasmic 604, pseudogene)
Gene: Miscellaneous RNA gene on chromosome 2 (69,516,751 to 69,517,046, forward strand). Ensembl gene ENSG00000244236.
Homologues: Orthologues: chimpanzee Metazoa_SRP (99% identical), macaque Metazoa_SRP (92% identical), rabbit Metazoa_SRP (62% identical). Paralogues in human: RN7SL1 (84% identical), RN7SL2 (84% identical), RN7SL3 (82% identical), RN7SL344P (81% identical), RN7SL45P (81% identical), RN7SL709P (81% identical), RN7SL333P (81% identical), RN7SL655P (81% identical), RN7SL336P (81% identical), RN7SL408P (81% identical), RN7SL786P (80% identical), RN7SL478P (80% identical), and 707 more.